NMUR2 (neuromedin U receptor 2)
Description:
G protein-coupled receptor for the neuropeptides neuromedin-U (NMU) and neuromedin-S (NMS). Functionally, is involved in regulation of feeding and energy balance (By similarity). Additionally may modulates blood pressure and smooth muscle contraction (By similarity). Mechanistically, upon ligand binding, couples to Galpha proteins, namely GNAQ/Gaq or GNA11/Ga11 and GNAI1/Gai subunits. GNAQ/Gaq or GNA11/Ga11 coupling leads to the activation of a phospholipase C (PLC), which hydrolyzes PIP2 (phosphatidylinositol 4,5-bisphosphate) into DAG (diacylglycerol) and IP3 (inositol trisphosphate), and subsequent intracellular calcium mobilization via IP3 receptors on the endoplasmic reticulum. GNAI1/Gai coupling inhibits forskolin-stimulated cAMP accumulation.
Synonyms: NMU-R2; TGR-1; NMU2R; TGR1; FM-4; FM4
Tractability: Small molecule: a high-quality ligand is known; it belongs to a druggable protein family. Antibody: its Gene Ontology location is reachable by antibodies, with high confidence; UniProt places it where antibodies can reach, with medium confidence; UniProt predicts a signal peptide or a membrane-spanning region; the Human Protein Atlas places it where antibodies can reach. PROTAC: a small molecule that binds it is known.
Target class: Peptide receptor (family A GPCR); Membrane receptor; Neuromedin U receptor; Family A G protein-coupled receptor; Short peptide receptor (family A GPCR)
Gene: Protein-coding gene on chromosome 5 (152,391,542 to 152,433,368, reverse strand). Ensembl gene ENSG00000132911.
Subcellular location: Cell membrane
Subcellular location (Human Protein Atlas): Plasma membrane
Pathways (Reactome):
Signal Transduction: G alpha (i) signalling events; G alpha (q) signalling events; Peptide ligand-binding receptors
Gene Ontology:
Molecular function: G protein-coupled receptor activity; neuromedin U binding; neuromedin U receptor activity; neuropeptide receptor activity; protein binding
Biological process: adenylate cyclase-inhibiting G protein-coupled receptor signaling pathway; arachidonate secretion; G protein-coupled receptor signaling pathway; neuropeptide signaling pathway; phospholipase C-activating G protein-coupled receptor signaling pathway; cell-cell signaling; central nervous system development; feeding behavior; positive regulation of calcium-mediated signaling; regulation of smooth muscle contraction; chloride transport
Cellular component: membrane; plasma membrane
Genetic constraint (gnomAD): Loss-of-function variants: 20 observed, 21.9 expected, observed/expected ratio (o/e) 0.91, 90% interval 0.64 to 1.33. The upper end of that interval is the gene's LOEUF score, 1.33, which puts it in group 5 of 6, group 1 being the genes least tolerant of losing a copy. Missense variants: 504 observed, 511.72 expected, observed/expected ratio (o/e) 0.98, 90% interval 0.92 to 1.06. Synonymous variants: 205 observed, 210.32 expected, observed/expected ratio (o/e) 0.97, 90% interval 0.87 to 1.09.
Homologues: Orthologues: chimpanzee NMUR2 (97% identical), macaque NMUR2 (95% identical), rabbit NMUR2 (79% identical), dog NMUR2 (77% identical), pig NMUR2 (76% identical), mouse Nmur2 (76% identical), rat Nmur2 (74% identical), tropical clawed frog nmur2 (63% identical), Drosophila melanogaster PK2-R1 (30% identical), Drosophila melanogaster PK2-R2 (30% identical), Drosophila melanogaster PK1-R (29% identical), Drosophila melanogaster CapaR (29% identical), and 2 more. Paralogues in human: NMUR1 (44% identical), NTSR1 (27% identical), TRHR (26% identical), MLNR (24% identical), GHSR (24% identical), GPR39 (22% identical), NTSR2 (21% identical), BRS3 (19% identical), NMBR (19% identical), EDNRB (19% identical), GRPR (19% identical), EDNRA (17% identical), and 3 more.
Diseases named in the same sentence as NMUR2 in open-access papers:
NMUR2 is named in the same sentence as 26 diseases in open-access papers, as found by Europe PMC text mining. Sharing a sentence is not in itself a finding about the gene and the disease. The quoted sentences say what the papers report.
Obesity (8 papers, 2009 to 2022). Accumulation of substantial excess body fat. "NMUR2 may represent a druggable target and a potential access point for the control of important neural pathways underlying food intake and ultimately obesity." (PMID 30151213, 2018). "Specifically, selective agonists for NMUR2 in peripheral tissue show promising long-term anti-obesity effects with fewer CNS-related side effects." (PMID 35440625, 2022). "Neuromedin U receptor 2 (NMU2), an emerging attractive target for treating obesity, has shown the capability in reducing food intake and regulating energy metabolism when activated." (PMID 36575163, 2022). "Taken together, this work indicates NMUR2 agonism has pharmacotherapeutic potential for addressing metabolic disorders, such as obesity." (PMID 30151213, 2018). "Taken together, these data suggest that NY0116 and NY0128 are promising tool compounds in targeting NMUR2 as a pharmacotherapy for obesity." (PMID 30151213, 2018). "Neuromedin U receptor 2 is an emerging attractive target for treating obesity." (PMID 36575163, 2022). "Neuroanatomical variability and individual differences in NMUR2 expression may underlie aspects of individual differences observed in BED and obesity." (PMID 30717427, 2019). "This suggests that NMUR2 agonists previously studied for obesity may suppress cocaine-evoked behavior." (PMID 30483076, 2018). "The clinical implications of our findings establish NMUR2 as a novel regulator of binge-type eating and therefore as a potential druggable candidate for the overconsumption behavior observed in BED and obesity." (PMID 30717427, 2019). "Additional studies are needed to determine the functional role of NMUR2 in the mesoaccumbens circuit, including its effects on BED and obesity." (PMID 30717427, 2019).
breast carcinoma (4 papers, 2017 to 2021). "Taken together, the data presented here suggest for the first time that NMU-associated oncogenic effects on breast cancer cells are possibly mediated by the receptor NMUR2." (PMID 28423716, 2017). "As a systematic analysis approach of signaling pathways and associated molecules affected by NMU in breast cancer is still missing we applied the luminal-like, NMUR2-positive SKBR3 gain-of-function model to perform a comprehensive whole genome expression analysis." (PMID 28423716, 2017). "In the present study, we demonstrate up-regulation of NMU expression in breast cancer compared to healthy breast tissues for the first time and show that high NMU mRNA expression is associated with poor outcome in breast carcinomas presenting strong NMUR2 expression." (PMID 28423716, 2017). "Similar to endometrial and breast cancer studies, our data point to NMUR2 as an important functional receptor in CRC cells." (PMID 34493299, 2021). "Further, our data propose that the receptor NMUR2 is likely to mediate NMU-related effects on breast cancer cells." (PMID 28423716, 2017). "To elucidate signaling pathways and genes that are regulated by forced NMU expression, we performed a comprehensive whole genome expression analysis for NMU in breast cancer employing the luminal-like, NMUR2-positive SKBR3 model." (PMID 28423716, 2017). "We provide evidence that NMU promotes motile characteristics while suppressing growth of NMUR2-positive breast cancer cells potentially contributing to progression of a subset of breast cancer cases." (PMID 28423716, 2017). "Based on these two in vitro models, we started functional analyses to decipher the biological role of NMU in dependency of NMUR2 expression in breast cancer cells." (PMID 28423716, 2017). "Next, the biological impact of NMU on breast cancer cells in relation to NMUR2 expression was analyzed." (PMID 28423716, 2017). "Interestingly, our study revealed that NMUR2 was expressed in all breast cancer subtypes except for basal-type carcinomas almost completely lacking NMUR2 transcript." (PMID 28423716, 2017). "We identified for the first time a putative NMU-mediated modulation of WNT-superfamily signaling associated with enhanced activation of the small GTPase RAC1 that may contribute to increased migration of NMUR2-positive SKBR3 breast cancer cells." (PMID 28423716, 2017). "Therefore, we hypothesized that NMU may have an oncogenic role driving the progression of NMUR2-positive breast carcinomas potentially representing a novel target for the development of future personalized therapeutic strategies." (PMID 28423716, 2017). "In light of the retrospective data suggesting a potential oncogenic role for NMU in a NMUR2-positive background, we next aimed at analyzing the functional impact of NMU on breast cancer cells in dependency of NMU receptor expression." (PMID 28423716, 2017). "Other studies confirmed that NMU promotes a motile phenotype and showed its growth-inhibitory effect in NMUR2-positive (SKBR3) but not NMUR2-negative (Hs578T) breast cancer cells, indicating the importance of NMUR2-related signalling." (PMID 31492042, 2019).
Anxiety (3 papers, 2012 to 2022). Intense feelings of nervousness, tension, or panic often arise in response to interpersonal stresses. "Stimulation of brain NMUR2 has been found to modulate anxiety-like behaviour and trigger stress-related molecular events by CRH exocytosis." (PMID 35631458, 2022). "Excessive grooming induced by icv NMU administration were abolished in the NMUR2 KO mice, an observation suggesting that NMUR2 plays a decisive role in stress/anxiety induction." (PMID 23227022, 2012).
endometrial cancer (3 papers, 2016 to 2023). Primary or metastatic malignant neoplasm involving the endometrium (mucous membrane that lines the endometrial cavity). "We identified that NMU and one of its receptors, NMUR2, are not only present in normal uterine endometrium but also co-expressed in endometrial cancer tissues, where the NMU level is correlated with the malignant grades and survival of patients." (PMID 26849234, 2016). "Using clinical samples from patients with endometrial cancer, we also confirmed the transcript level of NMUR2 is higher than that of NMUR1 especially in the high grade tumors, consistent with the receptor profiles shown in the normal mouse uterus." (PMID 26849234, 2016). "In the present study, we found that NMU and NMUR2 are co-expressed in the mouse normal uterine endometrium and also in human endometrial cancer tissue samples." (PMID 26849234, 2016). "Furthermore, the level of NMUR2 was much higher than that of NMUR1 in all three endometrial cancer lines, suggesting that NMUR2 is also the main receptor type involved in conducting NMU signaling in these cells." (PMID 26849234, 2016). "NMUR2 is a receptor that enhances NMU-mediated cell motility and invasion in human pancreas and endometrial cancer cells." (PMID 36785669, 2023). "In line with two recent studies, also NMUR2 was identified as the receptor responsible for NMU-mediated enhancement of cellular motility and invasiveness in human pancreatic and endometrial cancer cells." (PMID 28423716, 2017).
alcohol use disorder (2 papers, 2016 to 2020). "The findings of a genome-wide allelic association study showed that polymorphisms in the NMUR2 gene are associated with alcohol use disorders suggest that the presented data can be translationally valid." (PMID 27139195, 2016). "We further examined the expression of NMU and NMU receptor 2 (NMUR2) in NAc and the dorsal striatum of high compared with low alcohol‐consuming rats, as this area is of importance in the maintenance of alcohol use disorder (AUD)." (PMID 31069918, 2020).
asthma (2 papers, 2022 to 2024). "Further functional biological studies related to the role of NMUR2 are needed to identify individuals at risk for asthma and COPD." (PMID 36543808, 2022). "Moreover, NMUR2 increases the risk of asthma development and suppresses COPD development." (PMID 36543808, 2022). "In conclusion, we demonstrated that the SNP rs2961757 of NMUR2 is the most common significant SNP in patients with asthma and COPD, and it has potentially opposing genetic effects." (PMID 36543808, 2022). "Further studies should focus on the function of NMUR2 and its clinical usefulness, including asthma treatment strategies beyond genetic profiling." (PMID 36543808, 2022). "We discovered that NMUR2 is a common gene involved in the development of asthma and COPD, with increased and decreased expression in asthma and COPD, respectively." (PMID 36543808, 2022). "We used a multinomial approach and identified a novel SNP rs2961757 on chromosome 5, which is located near NMUR2, as a potentially common gene with opposing effects in patients with asthma and COPD." (PMID 36543808, 2022). "From this perspective, NMUR2 might be a genetic marker for the differentiation of patients with asthma and COPD." (PMID 36543808, 2022). "The mRNA expression of NMUR2 in the U-BIOPRED and GEO datasets also increased in patients with asthma and decreased in those with COPD." (PMID 36543808, 2022). "Since the nature of airway inflammation in asthma and COPD differs, primarily eosinophilic in asthma and neutrophilic in COPD34, the expression of NMUR2 may be opposing in COPD and asthma considering the effects of NMUR2 in airway inflammation." (PMID 36543808, 2022). "NMUR2 may mediate the effects of NMU in the lungs, leading to type 2 cytokine responses and eosinophilic airway inflammation, which are involved in the development of asthma." (PMID 36543808, 2022).
breast tumor (2 papers, 2017 to 2019). "Using an in silico dataset comprising 1,195 samples, high NMU expression was identified as an indicator of poor outcome in breast tumors showing strong NMUR2 expression." (PMID 28423716, 2017).
epilepsy (2 papers, 2019 to 2022). A brain disorder characterized by episodes of abnormally increased neuronal discharge resulting in transient episodes of sensory or motor neurological dysfunction, or psychic dysfunction. "DLG2 belongs to the gene motif “BGNADP”, which is a network associated with ID and epilepsy, including also BTD, GALNT10, NMUR2, AUTS2, and PTPRD." (PMID 35627244, 2022).
ovarian carcinoma (2 papers, 2015 to 2019). A malignant neoplasm originating from the surface ovarian epithelium. "During PCR amplification of full-length NMUR2 from a human ovarian cancer cDNA pool, a short but dominant splice variant was found and cloned." (PMID 26317338, 2015). "Validation of NMU, NMUR1, and NMUR2 levels in samples of patients with ovarian cancer and in paired normal adjacent tissues (n = 100) showed that in this type of tumour, the level of NMU expression was elevated (941 fold)." (PMID 31492042, 2019). "Based on our previous finding that NMU signaling is present in the ovary, here we further have shown that both the transcript and protein levels of NMU and NMUR2 were increased in ovarian cancer tissue samples." (PMID 26317338, 2015). "Following this, we further found the transcripts of NMU and NMUR2 are significantly induced in the ovarian cancer tissues; this increase was by 941 folds and 5 folds, respectively on average compared to those in the adjacent normal controls." (PMID 26317338, 2015). "Overexpression of NMUR2S significantly suppresses NMU downstream signaling and the proliferation rate of SKOV-3 ovarian cancer cell line, which expresses NMUR2 dominantly and NMUR1 moderately." (PMID 26317338, 2015). "We identified NMUR2S from the human ovarian cancer cDNA and have also previously showed that the NMUR2 level can be regulated by gonadotropin signaling in the ovary, the prominent organ for steroid hormone production." (PMID 26317338, 2015). "Indeed, we did demonstrate that NMUR2S is co-expressed together with NMUR2 in both the cancer and adjacent normal tissues harvested from patients with ovarian cancers." (PMID 26317338, 2015). "Taken together, up-regulation of both NMU and NMUR2 in ovarian cancers as shown by our findings suggests that over-activation of NMU signaling may be involved in promoting ovarian tumorigenesis." (PMID 26317338, 2015). "We recently identified a novel truncated NMUR2 derived by alternative splicing, namely NMUR2S, from human ovarian cancer cDNA." (PMID 26317338, 2015). "Taken together, these findings suggest that up-regulation of NMU signaling may help promoting ovarian cancer progression and that this effect can be reversed by introduction of NMUR2S, which can potentially heterodimerize with NMUR2 and NMUR1 to dampen NMU signaling." (PMID 26317338, 2015).
pancreatic cancer (2 papers, 2013 to 2019). "The co-expression of NMU and NMUR2, validated at the mRNA and protein levels, was also correlated with increased invasiveness and metastatic potential in pancreatic cancer cells (i.e., ASPC1, Capan1, Colo357, SU86.86, BxPC3, Capan1)." (PMID 31492042, 2019). "The NMUR1 expression was found at the same low level in all pancreatic tissues, but the amount of NMUR2 mRNA detected in pancreatic cancer tissues was 149 times higher compared to healthy tissues." (PMID 31492042, 2019). "The immunohistochemical staining showed neither NMU nor NMUR2 immunoreactivity in the normal pancreas, while in the pancreatic cancer tissues, there was very high cytoplasmic staining of NMU and NMUR2, which was also detected in the cell membrane." (PMID 31492042, 2019).
Alzheimer disease (1 paper, 2017). A progressive, neurodegenerative disease characterized by loss of function and death of nerve cells in several areas of the brain leading to loss of cognitive function such as memory and language. "These genes include CACNA1C, LRP1, PLCB2, GRIN2A, and NMUR2, which are involved in pathways such as Alzheimer’s disease, long-term potentiation, calcium signaling, and transmission across chemical synapses." (PMID 29184056, 2017).
Arthritis (1 paper, 2012). Inflammation of a joint. "Similarly, we have shown here that autoantibody-induced arthritis was unimpaired in these same Nmur1/Nmur2-deficient mice." (PMID 22314006, 2012). "Mice lacking NMUR1, NMUR2 or both receptors developed arthritis in an essentially indistinguishable way from control mice." (PMID 22314006, 2012).
colon cancer (1 paper, 2019). "In our investigations of colon cancer cells (HT29), we found that NMU and NMUR2 are co-expressed in colon cancer cell lines with induced EMT." (PMID 31492042, 2019).
colorectal cancer (1 paper, 2022). A primary or metastatic malignant neoplasm that affects the colon or rectum. "The latest study found for the first time that NMUR2 activation promoted signaling in colorectal cancer (CRC) cells, and that NMU improves the mobility and invasiveness of NMUR2-positive CRC cells." (PMID 35273971, 2022).
migraine (1 paper, 2020). "PLCE1 and NMUR2, whose variants showed noteworthy association with migraine susceptibility, were found to be involved in two pathways called “positive regulation of cytosolic calcium ion concentration” and “inositol phosphate-mediated signaling” detected in our study." (PMID 32046629, 2020).
osteoarthritis (1 paper, 2022). A noninflammatory degenerative joint disease occurring chiefly in older persons, characterized by degeneration of the articular cartilage, hypertrophy of bone at the margins and changes in the synovial membrane. "Neuromedin U (NMU) and NMU receptors (NMUR1 and NMUR2) are associated with obesity-related disorders and found in mast cells (MCs), which are elevated in osteoarthritis." (PMID 36232539, 2022).
papillary renal cell carcinoma (1 paper, 2023). A rare subtype of renal cell carcinoma, arising from the renal tubular epithelium and showing a papillary growth pattern, which typically manifests with hematuria, flank pain, palpable abdominal mass or nonspecific symptoms, such as fatigue, weight loss or fever. "BDKRB1, NMUR2, PMCH, and SAA1 may contribute to the occurrence and development of papillary renal cell carcinoma." (PMID 36785669, 2023).